PTK7 (protein tyrosine kinase 7 (inactive))
Diseases named in the same sentence as PTK7 in open-access papers (continued):
Sharing a sentence is not in itself a finding about the gene and the disease.
cancer (continued). "PTK7 levels need to be tightly controlled to enable migration of HT1080 cancer cells." (PMID 24618420, 2014). "Protein tyrosine kinase-7 (PTK7) is upregulated in many common human cancers." (PMID 24587299, 2014). "Similarly, we observed that PTK7 mAbs exhibited comparable anti-cancer effects to PTK7 knockdown." (PMID 39936972, 2025). "PTK7 is overexpressed in various cancers and is associated with oncogenic functions;21,38 however, the development of blocking antibodies or small-molecule inhibitors has been challenging owing to the lack of catalytic activity of PTK7." (PMID 40987771, 2025). "In ESCC cell lines with high PTK7 expression, overexpression of PTK7 inhibited cancer cell progression, in contrast to ESCC cell lines with lower PTK7 expression levels, leading to the hypothesis that ESCC cell malignancy may initially increase and then decrease with PTK7 expression." (PMID 39474113, 2024). "Additionally, PTK7 could enhance the invasive properties of cancer cells by upregulating MMP9 through activating AP-1 and NF-κB in ESCC." (PMID 39474113, 2024). "However, the future of anti-cancer therapy targeting PTK7 remains promising." (PMID 39474113, 2024). "Targeting PTK7 could be suitable for specifically targeting Wnt responder CSCs in cancers." (PMID 37190019, 2023). "Although the role of PTK7 in polarity establishment and coordinated cell movements is well known, our findings linking PTK7 to the focal adhesion signaling pathway to regulate cytoskeletal reorganization shed more light on the function of PTK7 to promote cancer progression." (PMID 37212485, 2023). "Therefore, we evaluated the changes in the proliferation of KYSE-30 cells due to PTK7 mAbs in a 3D model using Matrigel, where, in addition to uncontrolled proliferation, cancer cells migrate into the extracellular matrix by adhesion of cell-surface adhesion receptors such as integrins." (PMID 36293051, 2022). "Thus, in some cancer types with comparable, or even higher, PTK7 expression, the suppressive effect of PTK7 on oncogenic characteristics may be apparent." (PMID 29867084, 2018). "Notably, given that Wnt signaling plays significant roles in human cancer and that a recent study has shown that knockdown of PTK7 can inhibit Wnt/β-catenin activity, it is conceivable that PTK7 may also be involved in cancer development and progression." (PMID 28545451, 2017). "However, PTK7 also has a tumor-suppressive role in some cancer types." (PMID 27689325, 2016). "Therefore, PTK7 plays an important role in the motility and invasivity of cancer cells." (PMID 24409301, 2014). "Therefore, the use of PTK7 siRNA, or other methods that counteract PTK7 function, may be valuable in the development of cancer therapeutic agents." (PMID 21103379, 2010). "Specifically, treatment with PTK7 mAbs 32-m and 43-m in an ESCC xenograft mouse model using KYSE-30 cells showed notable anti-cancer effects." (PMID 39936972, 2025). "Of the genes whose function is related to the Wnt/β-catenin signaling pathway, we focused on PTK7, as it showed the most significant correlation with FOXP4 in OV and most other cancer types in TCGA." (PMID 38740744, 2024). "We review the most recent data assigning to PTK7 a prominent role in cancer progression as well as current preclinical and clinical targeting strategies against RTK family pseudokinases including PTK7." (PMID 38773263, 2024). "PTK7 amplifies the activation of FGFR1 and EGFR, crucial in transmitting oncogenic signals that foster cancer initiation and metastasis." (PMID 38740744, 2024). "Specifically, our data revealed that in the PTK7‐knockdown CL1‐5 cells, cancer cells with exogenous overexpression of miR‐503 still exhibited less invasive phenotypes." (PMID 37212485, 2023). "Previous studies have reported the interaction between PTK7 and ROR2, FGFR1, or EGFR in cancer cells." (PMID 37569547, 2023).
cancer (continued). "Protein tyrosine kinase 7 (PTK7), a catalytically defective receptor tyrosine kinase (RTK), is often upregulated in various cancers." (PMID 37569547, 2023). "The Sgc8 aptamer is an active tumor-targeting ligand that binds to protein tyrosine kinase 7 (PTK7), a transmembrane receptor for cancer cells that is highly expressed in T cell ALL cell lines, such as CCRF-CEM cells and Molt-4 cells." (PMID 36612296, 2023). "The overall somatic alteration frequency of PTK7, including copy number alterations, was calculated to reach about 3.54% for CRC and up to 10% for other cancers." (PMID 35163215, 2022). "Protein tyrosine kinase-7 (PTK7) is an important member of the receptor tyrosine kinase superfamily and has been demonstrated to be overexpressed in various types of cancer." (PMID 36544906, 2022). "Protein tyrosine kinase 7 (PTK 7) is a membrane receptor, which can be found in various kinds of cancers." (PMID 33588855, 2021). "Previous studies in mammals have found that the extracellular, N-terminal region of Ptk7 can be cleaved from the cell membrane by MMP and ADAM metalloproteinases to promote migration in cancer cells." (PMID 34887411, 2021). "Among the top 10 DRGs identified from TCGA-STAD dataset, six are GC related (E2F1, AK1B10, CEBPA, PTK7, RASAL1, GKN), and three are cancer related (DPCR1, GGT6, RAB25)." (PMID 29745833, 2018). "Ptk7 is cleaved by a membrane type matrix metalloprotease (MT1-MMP) affecting its function in both zebrafish and human development, and cancer cell metastasis." (PMID 27438854, 2016). "Overall, it is likely that MT1-MMP proteolysis of PTK7, ADAM and γ-secretase promotes cancer progression by stimulating the CREB activity." (PMID 24618420, 2014). "Understanding these mechanisms will shed additional light on the role that PTK7, alone as well as in combination with MT1-MMP, ADAMs and γ-secretase, plays in cancer cell migration." (PMID 24618420, 2014). "Moreover, research has predominantly focused on broadly expressed pan-cancer biomarkers, such as PTK7, nucleolin, and EGFR, while studies specifically addressing biomarkers unique to rare cancers remain scarce." (PMID 41560835, 2026). "Our analysis of drug repurposing network and RNAi screening suggested PTK7 as a potential therapeutic target with no FDA approved drugs in cancer." (PMID 41979058, 2026). "While these findings have not yet been translated into clinical applications, the potential significance of PTK7 and PTK7-targeted aptamers in cancer cell detection and diagnosis should not be overlooked." (PMID 39474113, 2024). "The therapeutic potential of other strategies, such as PTK7 monoclonal antibodies, remains uncertain without pan-cancer species trials." (PMID 39474113, 2024). "Despite numerous preclinical studies and clinical trials targeting PTK7 in cancer therapy, there has been no significant impact on the clinical treatment paradigm for either cancer type." (PMID 39474113, 2024). "Further preclinical studies are needed to investigate PTK7’s involvement in cancer development, addressing the current lack of understanding of molecular interactions and uncovering new signaling pathways with therapeutic relevance." (PMID 39474113, 2024). "In 2020, a study confirmed the allogeneic anti-PTK7 CAR-T cells could exhibit anticancer properties both in vitro and in immunocompromised mouse xenograft models of cancer." (PMID 39474113, 2024). "miR-503 regulates PTK7/FAK signaling to control the invasion and dissemination of cancer cells." (PMID 39474113, 2024). "Although PTK7 is well known to be required in collective migration, its functional roles in promoting cancer progression have not been well elucidated." (PMID 37212485, 2023). "Therefore, some catalytically defective RPTKs involved in tumorigenesis, such as PTK7, Erb-B2 receptor tyrosine kinase 3 (ErbB3), and EPH receptor A10 (EphA10), are considered target molecules for cancer therapy." (PMID 36293051, 2022).
cancer (continued). "Noticeably, new potential targets including proteins expressed by cancer stem cells (CSC), such as PTK7, ephrin-A4, 5T4 and in the TME, such as CD205, CD25, B7-H3, are under investigation with some of these that already reached clinical phases of drug development." (PMID 35953604, 2022). "The PTK7-GEMs group showed the brightest terminal deoxynulceotidyl transferase nick-end-labeling (TUNEL) signals, indicating the induction of marked cancer cell apoptosis." (PMID 36471380, 2022). "The immunohistochemistry assay determined a carcinoma that exhibited a diffuse and strong cytoplasmic staining for PTK7 that was negative for HER2 (score 0 to 1+)." (PMID 35269608, 2022). "Thiol groups of Sgc8 aptamer (with affinity to protein tyrosine kinase 7 (PTK7), a membrane protein overexpressed on the cancer cell surface), reacted with methacryloyl‐modified N‐acetyl mannosamine analogs that were conjugated to the sialic acids on the Mφs surface." (PMID 33898169, 2021). "PTK-7 expression was noted in 56.7% of patients and was stronger in cancer tissue than in matched non-cancerous mucosa." (PMID 31820857, 2020). "Therefore, cancer‐related RTK become preferable targets for ADC development, e.g. RON, PTK7, FLT3, FGFR2, FGFR3, ERBB3, KIT and EPHA2." (PMID 31116512, 2019). "Protein tyrosine kinase 7 (PTK7), also known as colon carcinoma kinase 4 (CCK-4), is a member of the catalytically defective receptor protein tyrosine kinase family and is upregulated in various cancers, where it is known to act as either an oncoprotein or a tumor suppressor." (PMID 29867084, 2018). "Therefore, a better understanding of the biphasic regulation of tumorigenesis by PTK7 will provide important information for the development of therapeutic means to control ESCC and other cancers that express PTK7." (PMID 29867084, 2018). "To further investigate a potential pro-metastatic effect of PTK7, we built a cellular model of PTK7 overexpression in PTK7-negative cancer cells and examined its impact on metastasis development in vivo." (PMID 25962058, 2015). "The PTK7 fragments would diffuse out into the extracellular space without a significant concentration in cancer tissues." (PMID 24587299, 2014). "PTK7 has been identified as a protein with an important role not only in embryogenetic tube formation, but also migration and invasion of endothelial and cancer cells invitro." (PMID 24987951, 2014). "In conclusion, suppression of PTK7 significantly increases apoptosis and inhibits cell proliferation in HCT 116 cells, indicating that PTK7 may play an important role in maintaining cancer cell viability." (PMID 21103379, 2010). "Efficacy studies in various cancer types with PTK7 overexpression showed that Sgc8c-M effectively induces sustained tumor regression in cell line-derived and patient-derived xenografts, outperforming unconjugated MMAE, the chemotherapy drug paclitaxel, and a PTK7-targeted antibody-drug conjugate." (PMID 40987771, 2025). "PTK7 signaling is regulated by proteolytic cleavage events that involves MT1-MMP (Membrane Type-1 Matrix MetalloProteinase), a well characterized enzyme highly expressed during cancer cell invasion and playing a central role in extracellular matrix degradation." (PMID 38773263, 2024). "The prognostic significance of PTK-7 expression in many cancers has not been settled." (PMID 31820857, 2020). "Furthermore, PTK7 has been identified as a protein with an important role not only in embryogenetic tube formation, but also migration and invasion of endothelial and cancer cells in vitro." (PMID 24409301, 2014). "Thus, our result documenting a potent antitumor effect of PTK7-CAR T cells adds PTK7 to the kind list of ROR1, which, as a member of Wnt signaling-related pseudokinases, had a characteristic enriched expression in TIC/CSCs and is suitable as a potential therapeutic target for cancer immunotherapy." (PMID 34475869, 2021).
cancer (continued). "Thus far, the focus has exclusively been on PTK7 function in cancer cells and tumor progression, but not on using it as a tool to prevent cancer invasion of tumor cells with high PTK7 expression, although PTK7 has been discussed as an attractive tumor marker and therapeutic target." (PMID 34502237, 2021). "Meanwhile, PTK7, as a direct target gene of miR-503, could activate FAK and paxillin, thus regulating cytoskeletal dynamics to promote cancer cell invasion and migration, but PTK7 was not involved in miR-503-induced EMT." (PMID 39474113, 2024). "PTK7 and MMP-9 are enriched at pericellular region of cancer cells but not around normal cells." (PMID 27689325, 2016).
tumor (80 papers, 2014 to 2026). "The expression of tumor-associated genes like PTK7 and MAGEA3 escalated, implying a potential increase in metabolic activities and nuclear functions during cellular transformation, correlating with elevated proliferation and enhanced viability in tumor cells." (PMID 38720887, 2024). "The gene sets enriched in high-PTK7-expressing tumours were HALLMARK MITOTIC SPINDLE (NES = 2.12, p < 0.001), HALLMARK APICAL JUNCTION (NES = 1.93, p < 0.001), and HALLMARK GLYCOLYSIS (NES = 1.74, p = 0.008)." (PMID 39335176, 2024). "PTK7 knockdown MDA-MB-468 cell bearing mouse model further demonstrated that PTK7-deficiency inhibits TNBC tumor progression in vivo." (PMID 34367983, 2021). "A possible interaction of PTK7 with Ror2 is likely not limited to NC cells, as PTK7 and Ror2 have also been implicated in tumor development and progression." (PMID 26680417, 2015). "Remarkably, in our study higher PTK7 expression in LN metastasis was not only significantly associated with a higher number of tumor-involved LN, but also with a significantly shorter DFS (96% (95%low vs 80% high after 24 months p = 0.016)." (PMID 24409301, 2014). "The gene sets enriched in low-PTK7-expressing tumours were HALLMARK ESTROGEN RESPONSE EARLY (NES = −1.99, p = 0.004), HALLMARK ESTROGEN RESPONSE LATE (NES = −1.84, p = 0.004), HALLMARK BILE ACID METABOLISM (NES = −1.71, p < 0.001), and HALLMARK FATTY ACID METABOLISM (NES = −1.70, p = 0.006)." (PMID 39335176, 2024). "PTK7 expression is associated with tumor size and lymph-node metastasis in BC." (PMID 37569547, 2023). "Similarly, PTK7-CAR T cells produced a large amount of IFN-γ and IL-2, which is positively associated with the expression level of PTK7 on respective tumor cells." (PMID 34475869, 2021). "Taken together, PTK7 seems to be linked to tumor progression and metastasis like the other genes." (PMID 24409301, 2014). "Interestingly, in normal organs, calcitriol was found to upregulate the expression of various stemness-related genes, including PTK7, whereas in tumor organs, calcitriol had minimal impact on PTK7 expression, indicating a loss of regulation by calcitriol in CRC." (PMID 39474113, 2024). "In SCLC, early investigational efforts are exploring CAR-T constructs directed against targets such as CDH17, GD2, and PTK7, which are selected based on tumor-enriched expression patterns similar to those leveraged by ADCs and T-cell engagers." (PMID 41562777, 2026). "Tumor‐bearing mice received a single 0.5 mg kg−1 dose of MedTACPTK7, which effectively reduced PTK7 levels in the tumor core, maintained for at least three days." (PMID 40305781, 2025). "Overall, these results underscore the promising pharmacokinetic profiles, biosafety and tumor suppression effects of MedTACPTK7, with PTK7 degradation contributing to extended survival in BC‐bearing mice." (PMID 40305781, 2025). "Consistent with Western blot data, PTK7 levels were substantially reduced in the tumor core but showed minimal change at the margins." (PMID 40305781, 2025). "The direct correlation between PTK7 expression and therapeutic response, combined with the enhanced crossfire effects in tumor-like architectures, supports the advancement of PTK7-directed therapy for clinical applications." (PMID 40885785, 2025). "Mice were subcutaneously injected with MDA-MB-231 cells to induce tumor formation, and anti-PTK7 mAbs (10 mg/kg) were administered intravenously twice a week for 3 weeks." (PMID 39936972, 2025). "Together, compared to the PTK7-negative A549 model, Sgc8c-M showed stronger tumor suppression in the PTK7-overexpressing NCI-H1975 model, both in vitro and in vivo." (PMID 40987771, 2025). "In vivo, PTK7 mAbs significantly reduced tumor volume and weight in a TNBC xenograft mouse model compared with controls." (PMID 39936972, 2025). "The results show that PTK7 mRNA levels were significantly higher in BC tumor tissues compared with adjacent normal tissues." (PMID 39936972, 2025).